IL17RC (interleukin 17 receptor C)
Description:
Receptor for IL17A and IL17F, major effector cytokines of innate and adaptive immune system involved in antimicrobial host defense and maintenance of tissue integrity (By similarity). Receptor for IL17A and IL17F, major effector cytokines of innate and adaptive immune system involved in antimicrobial host defense and maintenance of tissue integrity. Receptor for IL17A and IL17F homodimers as part of a heterodimeric complex with IL17RA. Receptor for the heterodimer formed by IL17A and IL17B as part of a heterodimeric complex with IL17RA. Has also been shown to be the cognate receptor for IL17F and to bind IL17A with high affinity without the need for IL17RA. Upon binding of IL17F homodimer triggers downstream activation of TRAF6 and NF-kappa-B signaling pathway. Induces transcriptional activation of IL33, a potent cytokine that stimulates group 2 innate lymphoid cells and adaptive T-helper 2 cells involved in pulmonary allergic response to fungi (By similarity). Promotes sympathetic innervation of peripheral organs by coordinating the communication between gamma-delta T cells and parenchymal cells. Stimulates sympathetic innervation of thermogenic adipose tissue by driving TGFB1 expression (By similarity). Binding of IL17A-IL17F to IL17RA-IL17RC heterodimeric receptor complex triggers homotypic interaction of IL17RA and IL17RC chains with TRAF3IP2 adapter through SEFIR domains. This leads to downstream TRAF6-mediated activation of NF-kappa-B and MAPkinase pathways ultimately resulting in transcriptional activation of cytokines, chemokines, antimicrobial peptides and matrix metalloproteinases, with potential strong immune inflammation. Primarily induces neutrophil activation and recruitment at infection and inflammatory sites (By similarity). Stimulates the production of antimicrobial beta-defensins DEFB1, DEFB103A, and DEFB104A by mucosal epithelial cells, limiting the entry of microbes through the epithelial barriers (By similarity). [Isoform 5]: Receptor for both IL17A and IL17F. [Isoform 6]: Does not bind IL17A or IL17F. [Isoform 7]: Does not bind IL17A or IL17F. [Isoform 8]: Receptor for both IL17A and IL17F.
Synonyms: IL17-RL; CANDF9; IL17RL
Tractability: Antibody: UniProt places it where antibodies can reach, with high confidence; its Gene Ontology location is reachable by antibodies, with high confidence; UniProt predicts a signal peptide or a membrane-spanning region. PROTAC: ubiquitination databases record sites on it.
Gene: Protein-coding gene on chromosome 3 (9,917,040 to 9,933,630, forward strand). Ensembl gene ENSG00000163702.
Subcellular location: Cell membrane
Pathways (Reactome):
Disease: SARS-CoV-2 activates/modulates innate and adaptive immune responses
Immune System: Interleukin-17 signaling
Gene Ontology:
Molecular function: coreceptor activity; interleukin-17 receptor activity; protein binding; signaling receptor binding
Biological process: interleukin-17A-mediated signaling pathway; interleukin-17-mediated signaling pathway; positive regulation of cytokine production involved in inflammatory response; protein K63-linked ubiquitination; T-helper 17 type immune response; defense response to fungus; granulocyte chemotaxis; positive regulation of interleukin-6 production
Cellular component: plasma membrane; cell surface
Genetic constraint (gnomAD): Loss-of-function variants: 52 observed, 84.32 expected, observed/expected ratio (o/e) 0.62, 90% interval 0.49 to 0.78. The upper end of that interval is the gene's LOEUF score, 0.78, which puts it in group 3 of 6, group 1 being the genes least tolerant of losing a copy. Missense variants: 957 observed, 923.8 expected, observed/expected ratio (o/e) 1.04, 90% interval 0.98 to 1.09. Synonymous variants: 439 observed, 411.29 expected, observed/expected ratio (o/e) 1.07, 90% interval 0.99 to 1.15.
Homologues: Orthologues: chimpanzee IL17RC (98% identical), macaque IL17RC (96% identical), dog IL17RC (77% identical), rabbit IL17RC (75% identical), guinea pig IL17RC (74% identical), rat Il17rc (68% identical), mouse Il17rc (63% identical), tropical clawed frog il17rc (29% identical), Caenorhabditis elegans ilcr-1 (12% identical), zebrafish il17ra1a (11% identical), zebrafish il17ra1b (10% identical), zebrafish il17ra2 (4% identical). Paralogues in human: IL17RE (21% identical), IL17RA (14% identical), IL17RD (10% identical), IL17RB (9% identical).
Diseases named in the same sentence as IL17RC in open-access papers:
IL17RC is named in the same sentence as 108 diseases in open-access papers, as found by Europe PMC text mining. Sharing a sentence is not in itself a finding about the gene and the disease. The quoted sentences say what the papers report.
chronic mucocutaneous candidiasis (8 papers, 2015 to 2023). "In humans, rare mutations in the genes encoding IL-17F, IL-17RA, IL-17RC, RORc and Act1 are strongly associated with chronic mucocutaneous candidiasis (CMC)." (PMID 26274976, 2015). "Thus, patients with autosomal recessive complete deficiencies in IL-17RA, IL17RC, or ACT1/TRAF3IP2 develop fully penetrant, severe, treatment-refractory mucosal infections by Candida species, termed chronic mucocutaneous candidiasis (CMC)." (PMID 34964702, 2022).
psoriasis (8 papers, 2017 to 2025). An autoimmune condition characterized by red, well-delineated plaques with silvery scales that are usually on the extensor surfaces and scalp. "Using the imiquimod-induced psoriasis model and the DMBA/TPA-induced skin tumorigenesis model, the present study found that the single knockin mutation of T779A of mouse IL17RA and knockout of mouse IL17RC prevented the development of psoriasis and tumorigenesis in the epidermis." (PMID 36009523, 2022). "Our data demonstrated that Il17ra(T779A)-KI and Il17rc-KO prevent the development of psoriasis and tumorigenesis in the skin, while the topical administration of centrinone does not have any effect." (PMID 36009523, 2022). "In the psoriasis model, compared to WT and Il17ra(T779A)-KI, Il17rc-KO dramatically suppressed epidermal thickening." (PMID 36009523, 2022). "Our study has confirmed the important role of the IL17RA/IL17RC heterodimer in promoting keratinocyte proliferation in psoriasis and skin papilloma models." (PMID 36009523, 2022). "In the analysis of significantly expressed genes between psoriasis and normal skin, IL17RC was considered as the most significantly overexpressed gene among the IL17 family members, followed by IL17RD, IL17RA, IL17F, and IL17RE." (PMID 36009523, 2022). "An imiquimod-induced psoriasis model was established in WT, Il17ra(T779A)-KI, and Il17rc-KO mouse strains." (PMID 36009523, 2022). "The proliferative signaling of keratinocytes is initiated by IL17 through recruitment of IL-17RA/IL-17RC and then Act1, which is assumed to explain the link between psoriasis and skin tumorigenesis." (PMID 36009523, 2022). "The expression of the IL-17 receptor, IL-17RA and IL-17RC, was confirmed on skin fibroblasts from psoriasis patients or healthy volunteers." (PMID 34616394, 2021). "Therapies that target IL17RC may be developed as potential therapeutic approaches to inhibit psoriasis and skin carcinogenesis." (PMID 36009523, 2022). "In contrast, deficiency of Il17rc completely abolished the thickening of the epidermis and the proliferation of keratinocytes, which verified the key role of IL17RA/IL17RC complex in the development of psoriasis." (PMID 36009523, 2022). "Our findings confirmed the pivotal role of IL17RC in psoriasis and skin tumorigenesis." (PMID 36009523, 2022). "We subsequently investigated whether neutrophils isolated from patients with active psoriasis could express/produce IL-17A, IL-17F, and/or IL-17RC mRNA, either constitutively or upon incubation for 20 h with IFNγ plus LPS, R848, or IL-17A." (PMID 29719541, 2018). "Therefore, our data are in agreement with the role of IL-17RA, IL-17RC, and IL-17RE in psoriasis, but we could highlight a differential expression pattern in the epidermis." (PMID 40243580, 2025). "We found that transcription levels of IL17A, IL17C, and IL17F were increased in psoriasis compared with normal skin, which was in parallel with their receptors IL17RA, IL17RC, IL17RD, and IL17RE." (PMID 36009523, 2022). "Additionally, miR-146a targets interleukin-17 receptor C (IL17RC), a key receptor involved in the inflammatory response in psoriasis, leading to the modulation of keratinocyte proliferation and migration." (PMID 40756258, 2025). "To investigate the cooperation between IL17 signaling and centriole duplication in epidermal proliferation, we established psoriasis and skin papilloma models in wild type (WT), IL17 receptor A (T779A) knockin (Il17ra(T779A)-KI), and IL17 receptor C knockout (Il17rc-KO) mouse strains." (PMID 36009523, 2022). "Our results confirm that UVB irradiation inhibits IL-17A/TNF-α-induced IL-6, IL-8, and CXCL-1 production in HDFs by decreasing the expression of IL-17RA and IL-17RC on fibroblasts through TGF-β1/Smad3 pathway, which reveals a new mechanism of the therapeutic action of UVB on psoriasis." (PMID 28217129, 2017).
psoriasis (continued). "UVB irradiation inhibits IL-17A/TNF-α-induced IL-6, IL-8, and CXCL-1 production in HDFs by decreasing the expression of IL-17RA and IL-17RC on fibroblasts through TGF-β1/Smad3 signaling pathway, which reveals a new mechanism of the therapeutic action of UVB on psoriasis." (PMID 28217129, 2017). "Similarly, we show that also neutrophils isolated from patients with active psoriasis do not express IL-17F, IL-17B, IL-17C, IL-17D, and IL-17E as well as IL-17RC mRNA when activated by R848, IFNγ plus LPS, and IL-17A in vitro." (PMID 29719541, 2018).
melanoma (7 papers, 2017 to 2023). A malignant, usually aggressive tumor composed of atypical, neoplastic melanocytes. "Similarly, expression analysis of Th17-associated genes in pre-treatment melanoma patient samples revealed that upregulation of IL17RC mRNA correlated with progressive or stable disease, whereas lower IL17RC mRNA correlated with partial or complete response to anti-PD-1." (PMID 33972557, 2021). "For melanoma, a previous study revealed that A20 mediated the effect of IL-17RC on the progression of xenograft tumor of B16 melanoma cells." (PMID 32968045, 2020). "In this study, we investigate the role of IL-17RC in two different murine cell lines—B16 melanoma and 4T1 mammary carcinoma, using a lentivirus vector-mediated shRNA knockdown (KD) approach." (PMID 28562353, 2017). "Triggered by IL-17RC knockdown (KD), B16 melanoma and 4T1 carcinoma cells inversely altered homeostatic tumor proliferation and tumor growth in vitro and in vivo." (PMID 28562353, 2017). "Together, our data suggest a positive role of IL-17RC in supporting the proliferation of B16 melanoma cells in vitro and in vivo." (PMID 28562353, 2017). "Therefore, in sharp contrast to its role in B16 melanoma, IL-17RC is a strong negative regulator of 4T1 homeostatic proliferation and invasiveness in vitro and in vivo." (PMID 28562353, 2017).
prostate carcinoma (6 papers, 2008 to 2023). A carcinoma that arises from epithelial cells of the prostate gland. "We have recently reported that different IL-17RC protein forms were differentially expressed in the immortalized normal prostatic epithelium and prostate cancer cells." (PMID 18928529, 2008). "It has been shown that the full-length IL-17RC formed homodimer and inhibited TNFα-induced apoptosis in prostate cancer cells." (PMID 18928529, 2008). "The isoform as detected by anti-IL-17RC intracellular domain antibodies (anti-ICD) was expressed at higher levels in androgen-independent prostate cancer cell lines (PC3 and DU145) than in androgen-dependent prostatic cell lines (RWPE-1, pRNS-1-1, MLC-SV40, and LNCaP)." (PMID 32537467, 2020). "Castrate mice without IL-17 receptor C (IL-17RC) prostate had lower rates of cellular proliferation as well as lower UBE2C protein level, indicating that UBE2C might play a role in TME of prostate cancer." (PMID 34950739, 2021).
rheumatoid arthritis (5 papers, 2018 to 2025). A chronic, systemic autoimmune disorder characterized by inflammation in the synovial membranes and articular surfaces. "IL-17RA rs4819554 was previously linked with response to etanercept in psoriatic arthritis, while IL-17RC rs708567 was associated with lupus arthritis and was described in Tunisians with rheumatoid arthritis." (PMID 34744511, 2021). "Soluble IL-17RC protein, which is a common receptor subunit for IL-17 and IL-17F, has been reported to exist and applied in rheumatoid arthritis via intraperitoneal injection." (PMID 34180764, 2021).
age-related macular degeneration (4 papers, 2014 to 2022). Age-related loss of vision in the central portion of the retina (macula), secondary to retinal degeneration. "For instance, age-related macular degeneration, a disease resulting in irreversible blindness in the elderly, has been correlated with the loss of methylation in the promoter region of the IL17RC gene, leading to increased IL17RC protein levels in the blood." (PMID 34910283, 2022). "Likewise, persistent existence of a stimulus, such as high expression of interleukin 17 receptor C (IL17RC) in eyes and peripheral blood cells in age-related macular degeneration, is also associated with increased GSK3 activity." (PMID 27493677, 2016). "Our previous study has suggested an elevated IL-17RC expression on several types of cells in the peripheral blood and retinal tissues from patients with Age-related Macular Degeneration." (PMID 24885153, 2014). "Our previous study identified a hypomethylated IL17RC promoter and elevated expression of IL17RC on CD14+ monocytes in the peripheral blood of patients with age-related macular degeneration." (PMID 24885153, 2014). "Since interleukin 17 receptor C (IL17RC) is highly expressed in tissues from age-related macular degeneration (AMD) patients, IL17RC signaling pathways are explored to evaluate Wnts/vascular endothelial growth factor (VEGF) expression and complement activity, which are pathological factors in AMD." (PMID 25089247, 2014).
asthma (4 papers, 2019 to 2022). "It was showed that variants in IL17RC are associated with increased risk of asthma (rs11917994, rs76234423 and rs279548) and atopy (rs279545, rs7627060, rs115461448, rs77569961) development." (PMID 31168303, 2019). "In the IL17RC, the T allele of rs279548 (OR: 1.30; 95% CI 1.02–1.64), the T allele of rs11917994 (OR: 1.40; 95% CI 1.09–1.79) and the A allele of rs76234423 (OR: 1.39; 95% CI 1.05–1.83), was positively associated with asthma." (PMID 31168303, 2019). "Also, the T allele of rs279548 was positively associated with asthma (OR: 1.30; 95% CI 1.02–1.64), atopy (OR: 1.62; 95% CI 1.05–2.50) and increased expression of the IL17RC in lung and whole blood tissues." (PMID 31168303, 2019). "In contrast, other asthma models mimicking more neutrophilic or severe asthma endotypes clearly demonstrated a pathological role for the IL-17A/IL-17F/IL-17RC axis in the modeled diseases." (PMID 35883573, 2022). "We hypothesized that soluble IL-17RC protein delivered by CS nanoparticles would have the positive effect on asthma, alleviating airway inflammation induced by IL-17 and IL-17F signal pathway." (PMID 34180764, 2021). "Interestingly, genetic score analyses demonstrated that combination variants in IL17RC and NFKB1 together increased the risk of asthma in comparison with the presence of these variants alone." (PMID 31168303, 2019). "Therefore, respiratory delivery of receptor proteins such as IL-17RC may be an attractive asthma intervention." (PMID 36145722, 2022). "Hence, delivering receptor proteins such as IL-17RC, through CS nanoparticles as a carrier, could be an attractive therapeutic intervention for asthma." (PMID 34180764, 2021). "To date, CS nanoparticles as IL-17RC protein vehicles for nasal administration of asthma mice have not yet been reported." (PMID 34180764, 2021). "There are no previous studies associating genetic variants in the IL17RC, RORC and NFKB with asthma, however, it is plausible to believe that variants that may interfere in the regulation of these genes play an important role in asthma." (PMID 31168303, 2019).
autoimmune disease (4 papers, 2020 to 2023). A disorder resulting from loss of function or tissue destruction of an organ or multiple organs, arising from humoral or cellular immune responses of the individual to their own tissue constituents. "Both IL-17A and IL-17F can generate homodimers or heterodimers and bind to heterodimeric IL-17RA and IL-17RC complexes, thereby activating downstream signaling transduction for host defense, autoimmune disease, or inflammation associated biological effects." (PMID 36274974, 2022). "IL-17RC is critical to signal transduction via IL-17A and the pathogenesis of autoimmune diseases." (PMID 37894114, 2023).
gastric cancer (4 papers, 2023 to 2024). A primary or metastatic malignant neoplasm involving the stomach. "Secondly, IL-17A also activates the NF-κB/NADPH oxidase 1 (NOX1) signaling pathway by binding to IL-17RA and IL-17RC, and promotes the cell cycle transition from G1 to S phase, thereby promoting the proliferation of gastric cancer cells." (PMID 39906741, 2024). "They do report an increase in IL-17RC with rIL17a treatment of AGS cells, and an increase in IL-17RC in human gastric cancer tissue compared to healthy tissue." (PMID 39588838, 2024). "Another study demonstrated that IL-17A can inhibit apoptosis and promote ROS production, sphere formation ability of cancer stem cells, and expression of stemness-related genes in gastric cancer AGS cells through the regulation of the IL-17RC/NF-ᴋB/NOX1 pathway." (PMID 38075398, 2024). "Interestingly, tissue microarrays of human stomach cancer samples clearly revealed increased expression of IL-17RC in GC compared with the normal stomach." (PMID 36125689, 2023). "IL-17RC expression was significantly higher in gastric cancer than in normal tissues." (PMID 36125689, 2023). "IL-17RC is upregulated in helicobacter pylori-induced gastric cancer tissues and human cancer tissues, participating in the IL-17A/IL-17RC axis and modulating the development of GC through the NF-κB/NOX1 signaling pathway." (PMID 39906741, 2024). "Our findings indicate that IL-17A promotes gastric cancer growth, oxidative stress, and CSC stemness by regulating the IL-17RC/NF-κB/NOX1 pathway." (PMID 36125689, 2023). "Using human microarray slides, we compared the degrees of IL-17RC expression in gastric cancer (tumor) and normal (non-tumor) tissues." (PMID 36125689, 2023). "However, the degree of IL-17RC expression in human gastric cancer tissues was not correlated with TNM stage." (PMID 36125689, 2023).
Autoimmunity (3 papers, 2011 to 2023). The occurrence of an immune reaction against the organism's own cells or tissues. "In vitro studies have shown that IL-17RC deficiency protects against autoimmunity." (PMID 37894114, 2023). "IL-17A and IL-17F which are highly homologous members of the IL-17 protein family and bind the same receptor complex consisting of IL-17RA and IL-17RC were often described as pro-inflammatory cytokines with redundant role in inflammation and autoimmunity." (PMID 21858022, 2011). "In addition, similar to other models of autoimmunity, depletion of IL17A and, more importantly, IL17RC may reduce the severity of eye disease after HSV-1 infection by affecting both IL17A and IL17F functions." (PMID 32516406, 2020).